PKD1P2 (polycystin 1, transient receptor potential channel interacting pseudogene 2)
Synonyms: HG2
Gene: Transcribed unprocessed pseudogene on chromosome 16 (16,356,224 to 16,377,507, forward strand). Ensembl gene ENSG00000227827.
Diseases named in the same sentence as PKD1P2 in open-access papers:
PKD1P2 is named in the same sentence as 10 diseases in open-access papers, as found by Europe PMC text mining. Sharing a sentence is not in itself a finding about the gene and the disease.
PKD1P2 shares sentences with these, for which no sentence is quoted: asthma (1 paper); breast carcinoma (1); chronic obstructive pulmonary disease (1); COVID-19 (1); depression (1); idiopathic pulmonary fibrosis (1); infection (1); kidney disease (1); lung diseases (1); pulmonary fibrosis (1).